IFNG (interferon gamma)
Diseases named in the same sentence as IFNG in open-access papers (continued):
Sharing a sentence is not in itself a finding about the gene and the disease.
colon carcinoma (continued). "Treatment of human colon cancer cells with interferon-gamma (IFN-γ) downregulates level of S100A4 mRNA in a time- and dose-dependent manner without associating with any cytotoxicities." (PMID 29069865, 2017). "We further demonstrate that miR-18a delivered by GNVs inhibits the growth of colon tumors that have metastasized to the liver by polarizing KCs to M1 cells (F4/80+IFNγ+IL-12+)." (PMID 27028860, 2016). "Mechanism study using mouse colon cancer cells, colon 26 cells reveals that the cells treated with TNFα and IFNγ pass through early apoptosis to late apoptosis/secondary necrosis but not through primary necrosis." (PMID 27342639, 2016). "Given the profound anti-colon tumor metastasis effect of miR-18a delivered by OGNVs, how miR-18a induces the expression of IFNγ in macrophages required further investigated." (PMID 27028860, 2016). "IFNγ-induced IRF8 acts in concert with NF-κB to regulate iNOS expression in both colon carcinoma and myeloid cells." (PMID 26497740, 2015). "Chronic IFNγ signaling promotes spontaneous colon cancer development through an iNOS-dependent mechanism." (PMID 26497740, 2015). "On the molecular level, the proinflammatory IFNγ and NF-κB signals induce iNOS expression in human colon cancer cells." (PMID 26497740, 2015). "Second, the 33-mer is transported across Caco-2 colon carcinoma cells in an un-cleaved form via transcytose, a process which is stimulated by interferon gamma." (PMID 23785500, 2013). "JAK2 has been shown to be activated in response to a wide variety of stimuli and AG-490 to block induced NOS2 expression in IL-1β/TNFα/IFNγ-stimulated human epithelial-like colon carcinoma DLD-1 cells and in IFNγ/LPS stimulated RAW cells." (PMID 18036230, 2007). "In addition to the antiviral activity, previous studies also showed IFNG had a dual pro-and anti-inflammatory effect in colon cancer (CC)." (PMID 36756126, 2023). "We treated C1498, a leukemia cell line, and MC38, a colon cancer cell line, with IFNγ." (PMID 36900204, 2023). "Incubation of CL40 colon cancer cells with IMC-KRASG12D together with HLA-A*11+ PBMC resulted in IMC-KRASG12D concentration dependent IFNγ, IL-2 and Granzyme B release as well as redirected T cell killing in a time- and dose-dependent manner with a mean EC50 value of 28.5 ± 25 pM." (PMID 36088370, 2022). "In addition, cholesterol can reduce IFNγ production in CD8+ T cells in colon cancer by increasing endoplasmic reticulum (ER) stress." (PMID 34385592, 2022). "Thus, multiple layers of regulatory mechanisms can affect IFNγ production by CD8+ T cells in the colon cancer microenvironment." (PMID 34385592, 2022). "Similarly, this experiment found that IFNG was significantly overexpressed in left-sided colon cancer through bioinformatics analysis." (PMID 35265525, 2022). "The molecular mechanisms involved in miR-18a-induced M1 macrophages were further studied and we found that miR-18a-mediated induction of macrophage IFNγ is required for inhibition of liver metastasis of colon cancer and that macrophage IRF2 is targeted by miR-18a." (PMID 27028860, 2016). "IFNγ and TNFα synergistically induce iNOS expression in human colon carcinoma cells." (PMID 26497740, 2015). "As expected, Ruxolitinib blocked IFNγ mediated STAT1 activation in human colon carcinoma cells." (PMID 26497740, 2015). "Using the human colon carcinoma T84 cell line and the murine myeloid J774 cell line as in vitro model systems, we observed that both IFNγ-activated Jak-STAT and LPS/TNFα-activated NF-κB are essential for iNOS induction in both the tumor cells and the myeloid cells." (PMID 26497740, 2015). "Because pSTAT1 enhances iNOS expression through the intermediate factor IRF8 in human colon carcinoma cells, we hypothesized that IFNγ activates IRF8 to regulate iNOS expression in myeloid cells as well." (PMID 26497740, 2015). "The IFNγ-sensitive colon carcinoma cell line HT29 served as positive control." (PMID 22919516, 2012).
colon carcinoma (continued). "However, apoptotic effects even in RH30 cells were smaller than in highly IFNγ-sensitive HT29 colon carcinoma cells that served as positive control." (PMID 22919516, 2012). "Whereas in normal macrophages and neoplastic myeloid and NK cells, IFNγ prevents apoptosis, it enhances apoptosis of tumour cells in malignancies such as pancreatic carcinoma, colon carcinoma and ovarian carcinoma." (PMID 12942126, 2003). "More importantly, in mouse MC38 and CT26 colon cancer models, treatment with TNFR2-PLGA-ADR potently inhibited the growth of tumor, which is associated with a decrease of TNFR2+ Tregs and, consequently, an increase of IFNγ+CD8+ cytotoxic T lymphocytes (CTLs) in the tumor tissue." (PMID 39247806, 2024). "IFNG might be a potential targeted therapy for cisplatin resistant colon cancer." (PMID 36756126, 2023). "Interestingly, in the syngeneic CT26 colon cancer allograft mouse model we observed additional involvement of IFNγ signaling and leukocyte activation-migration in the tumor immune micro-environment, which could not be addressed in the in vitro treatment setup." (PMID 33499163, 2021). "Previous research showed in tumor-infiltrating cytotoxic T lymphocytes (CTLs) in human colon carcinoma that SUV39H1 mediated H3K9me3 marks at the promoters of CTL effector genes (e.g., GZMB, PRF1, FASLG, and IFNG)." (PMID 40059829, 2025). "In an experimental colon carcinoma model in BALB/c mice, oral administration of L. casei ATCC 393 led to a significant increase in interferon gamma (IFN‐γ) in Peyer’s patches (PPs) 3 and 7 days post–CT26 inoculation." (PMID 41221154, 2025). "To explore this in human tumours, we performed analysis of publicly available spatial transcriptomic datasets from the 10X Genomics Visium platform to investigate IFNγ response and CD8-monocyte gene signatures on human lung and colon cancer samples." (PMID 39746898, 2025). "These engineered OMVs not only recruited cytotoxic T lymphocytes (CTLs) to the tumor site but also induced interferon-gamma (IFN-γ) secretion, resulting in improved anticancer effects in a mouse colon cancer model." (PMID 40317075, 2025). "An inflammatory cell model was established by LPS/IFNγ-stimulated RAW264.7 macrophages to observe the anti-inflammatory effect of DEH, while colon cancer cell lines were used to observe the anticancer activity of DEH." (PMID 40468178, 2025). "Intriguingly, high B2M expression showed significantly better prognosis than low B2M expression in colon cancer (p = 0.0021) similarly with CD8A, IFNG and TLR4." (PMID 38557819, 2024). "We crossed IFNγ+/− mice with IFITM3 cKO mice (to generate IFNγ+/− cKO mice) and inoculated them with MC38 murine colon cancer cells." (PMID 38167862, 2024). "Upon fludarabine treatment, decreased STAT1 mRNA levels in both murine colon cancer cells were observed, and more importantly, the stimulated expression of IFI35 by IFNγ was attenuated." (PMID 37380972, 2023). "To determine the effect of IFNG and its inhibitor glucosamine on the chemosensitivity of cisplatin in colon cancer, combined with the IC50 of cisplatin (25μmol/L), we examined the survival of cisplatin resistant DLD-1 after treatment with IFNG or glucosamine." (PMID 36756126, 2023). "Our data have demonstrated that IFNγ enhanced IRF3/7 expression and upregulation of IRF7 increases the expression of IFI35 in both murine colon cancer cells." (PMID 37380972, 2023). "CYP19A1 knockdown boosted tumor-infiltrating CD8+ T cells and enhanced GzmB and IFNγ production, indicative of CD8+ T cells-elicited adaptive immunity against colon cancer, which were amplyfied in combination therapy." (PMID 37055842, 2023). "Besides, IFNG might be a potential targeted therapy for cisplatin resistant colon cancer." (PMID 36756126, 2023).
colon carcinoma (continued). "Lastly, for colon tumors, we found that tumors with PTEN HemDel had downregulated immune-related pathways, including response to interferon-gamma, lymphocyte-mediated immunity, adaptive immune response, and natural killer cell-mediated immunity." (PMID 36977733, 2023). "Some bacterial strains from healthy human donor feces can promote IFNγ+CD8+ T cells in the intestine and enhance the efficacy of ICB in colon cancer-bearing mice." (PMID 34385592, 2022). "Aside from Th1 cells, other human colon cancer-infiltrating CD4+ T-cell subsets, including Th17 cells, Th22 cells, and Tregs, can express IFNγ." (PMID 34385592, 2022). "IFNγ and its signaling induce PD-L1 in TNBC, IFNα upregulates PD-L1 in dendritic cells, and TNFα upregulates PD-L1 in prostate and colon cancer cells." (PMID 35053979, 2022). "In fact, IL-33 can suppress murine colon cancer growth and metastasis by upregulating CD40L and promoting IFNγ production." (PMID 34638950, 2021). "Different inflammatory proteins are also suppressed in colon cancer tissues, including interleukin-4 (IL-4), IL-6, IL-18, TNF-α, and interferon gamma (IFN-γ)." (PMID 34163519, 2021). "For example, interferon-gamma (IFN-γ) can stimulate expression of programmed death-ligand 1 (PD-L1) in lung and colon cancer cell lines." (PMID 34884543, 2021). "Vice versa, colon cancer cells were able to induce secretion of cytokines (TNFα, IL10, IFNγ) and metastasis-related factors (VEGFC, MMPs) in MSC via activation of Wnt signaling which in turn resulted in activation of Wnt pathways in colon cancer cells." (PMID 27608835, 2016). "The new sequences were tested for their ability to induce cell death in an IFNγ-sensitive, active-STAT3-dependent colon carcinoma cell line." (PMID 22423663, 2012). "We reported recently that a combination of TNFR2 blocking antibody M861 (200 μg per mouse) and CpG oligodeoxynucleotides synergistically inhibited tumor growth in the mouse CT26 colon cancer model by reducing the TNFR2+ Tregs and increasing tumor-infiltrating IFNγ+CD8+ CTLs." (PMID 39247806, 2024). "We found that IFI35 was induced by IFNγ at both RNA and protein levels but not affected by LPS, poly IC, and poly A:D in murine colon cancer cells." (PMID 37380972, 2023). "Thus, IRF7 was a unique transcription factor that was stimulated by IFNγ and drove the expression of IFI35 in both murine colon cancer cell lines." (PMID 37380972, 2023). "The combination strategy was evaluated in mice bearing colon carcinoma cells (CT26) tumors following their weight, tumor volume, interferon-gamma (IFN-γ), and tumor necrosis factor-alpha (TNF-α) levels in the serum and produced by splenocytes exposed to CT26 tumor cells." (PMID 36046055, 2022). "Given that IFNGR1 palmitoylation is essential for its interaction with AP3D1 and subsequent IFNGR1 lysosomal sorting and degradation in colon cancer, suppression of IFNGR1 palmitoylation can restore cancer IFNγ signaling integrity and sensitize colorectal cancer cells to immunotherapy." (PMID 34385592, 2022). "Later, the specificity of 1MT for IDO1 was controversially discussed as it failed to block IDO1 activity in IFNγ-treated HeLa cells as well as in protein isolates of primary human colon cancer." (PMID 33920868, 2021). "IFNγ did not display single agent activity in colon cancer, although promising results were obtained for the 5-FU/IFNγ combination for treatment of advanced hepatocellular carcinoma." (PMID 32575843, 2020). "In colon carcinoma cells, IRF8 induced by IFNγ sensitizes them to Fas-mediated apoptosis, but the silencing of the IRF8 gene by methylation of its promoter region renders them resistance to IFNγ-mediated apoptosis." (PMID 21261980, 2011). "To investigate whether loss of ERH abolishes ISG induction across species and cell types, we performed 3′ mRNA QuantSeq in IFNγ-treated or non-treated RKO-iCas9 cells (human colon carcinoma) and RAW 264.7-iCas9 cells (murine macrophage)." (PMID 40586312, 2025).
colon carcinoma (continued). "Moreover, bystander killing of carcinoembryonic antigen (CEA)‐low colon cancer cells mediated by CD3xCEA bsAbs was suppressed by neutralizing antibodies targeting IFNγ but not those against FasL." (PMID 40178291, 2025). "Therefore, we first investigated whether the colon cancer cell line HCT116 and the hepatocellular cancer cell line Huh7 were able to express and to conjugate both endogenous FAT10 upon treatment with IFNγ and TNF and overexpressed FLAG-tagged FAT10." (PMID 37604583, 2023). "The identification of strategies to promote the enzymatic activity of WHSC1 in colon tumors thus appeared as a promising strategy to trigger selectively the antitumor properties of IFNγ in colon tumors without enhancing its potential involvement in immunosuppressive processes." (PMID 36428508, 2022). "The biological significance of APC-derived IFNγ has not been defined in colon cancer immunity." (PMID 34385592, 2022). "We obtained a panel of ovarian, breast, cervical, uterine and colon tumor fragments, cancer-types previously shown to present NGcGM3 at their surface, and upon 48 or 72h coculture with CAR h3 T cells versus untransduced (UTD) T cells, we evaluated IFNγ production." (PMID 35990626, 2022). "Transcriptome analysis of 57 advanced colon cancer samples revealed that one of the non-T cell inflamed subtypes (group 4) had low expression of CD8a, IFNG and GZMB with high expression of SCD1 and CTNNB1(β-catenin) and its downstream molecules including VEGFA and TCF12." (PMID 35793868, 2022). "Therefore, unlike IFNγ-activated pSTAT1, NF-κB directly binds to the iNOS promoter region to activate iNOS gene transcription in both human colon carcinoma and murine myeloid cells." (PMID 26497740, 2015). "On the other hand, we have not verified the cell experiments and mouse tumorigenesis experiments, and have not further explored the mechanism of NOS2, IFNG and ALOXE3 in the occurrence and development of colon cancer." (PMID 35265525, 2022). "As in the early phase of DSS induction, colonic tumor IL-6 (P<0.05) and possibly IL-11 (P = 0.07) mRNA expression was higher in Iron/DSS compared with Control/DSS mice but not TNF or IFNγ." (PMID 24223168, 2013). "Based on the differences found, new hpdODNs were designed and tested for their STAT3/STAT1 discrimination ability by measuring SW480 colon carcinoma cell death and absence of inhibition of STAT1-dependent IFNγ-induced cell death." (PMID 22423663, 2012). "To address this hypothesis, we compared TIL and paired PBMC function, by analyzing NK cell IFNγ production and degranulation activity in the presence of the MHC class I non-expressing K562 cells or with EGFR+ SW480 colon carcinoma target cells in the presence of Cetuximab in an ADCC assay." (PMID 36341402, 2022).
depression (250 papers, 2010 to 2026). "Both animal models and clinical studies demonstrate an increased inflammatory milieu associated with depression, including increased levels of interleukin-1beta (IL-1b), IL-6, tumor necrosis factor-alpha (TNFa), and interferon-gamma (IFN-g)." (PMID 39297528, 2024). "Interleukin-1 (IL-1), interferon-gamma (IFN-γ), acute-phase associated proteins and tumor cytokines have now been reported to be associated with depression disorder." (PMID 34890365, 2021). "A study in patients with hepatitis C treated with IFN-α demonstrated that carriers of IFNG (+874) T allele are more likely to present IFN-α-induced depression." (PMID 30662368, 2018). "Secretion of pro-inflammatory cytokines such as interleukin (IL)-1, tumor necrosis factor alfa (TNF-alfa) and interferon gamma (IFN-gamma) is associated with major depression." (PMID 28228811, 2016). "An additional study found that patients are more likely to develop symptoms of depression following immunotherapy if they harbored the “high producer” allele (IFNγ + 874, T allele) that is associated with elevated IFNγ expression." (PMID 27142940, 2016). "We previously reported an association between high producer (T) allele of IFNG (+874) T/A gene with the risk of IFN-alpha – associated depression." (PMID 25346938, 2014). "We reported the association of high producer (T) allele of IFNG +874) gene with increased risk of IFN-alpha associated depression." (PMID 25346938, 2014). "IFNγ is considered to be the prototypical inducer of IDO in a variety of cells as well as in clinical situations in which inflammation-associated depression occurs." (PMID 21810259, 2011). "The apparent reason the parasite causes depression is due to a host response to the infection, where interferon gamma blocks Toxoplasma gondii growth by inducing indoleamine-2,3-dioxygenase activation and tryptophan depletion, resulting in reduced brain serotonin production." (PMID 38394236, 2024). "In addition, a higher risk of depression has been linked to higher levels of Interferon gamma (IFN-γ), Interleukin 2 (IL-2), TNF-α as pro-inflammatory cytokines, and inflammatory markers as C-reactive protein (CRP)." (PMID 37386551, 2023). "Likewise, the correlation showed impairment of habituation memory and depression behavior associated with brain cyst load and elevated systemic levels of IFNγ and TNF." (PMID 35572567, 2022). "Furthermore, a single nucleotide variant in the IFNG gene was recently reported to elevate the risk of depression in the context of clinical IFN-α treatment." (PMID 33717157, 2021). "In addition we have also shown that greater interferon-gamma responses to surgery were associated with increased risk of depression 12 months after CABG surgery." (PMID 27552993, 2017). "Major depression is associated with an increased secretion of IFNγ." (PMID 21118505, 2010). "IFNγ is considered to be the prototypical inducer of IDO in a variety of cell types as well as in clinical situations in which inflammation-associated depression occurs." (PMID 20678226, 2010). "Furthermore, it has recently been proposed that a supraspinal decrease in BDNF levels is associated with an increase in serum IFNγ, which could therefore be used as an early peripheral marker for depression." (PMID 37530884, 2023). "Patients with depression exhibit elevated levels of pro-inflammatory cytokines (IL-6, IL-8), interferon-gamma (IFN-γ), and TNF-α." (PMID 40699781, 2025). "IL-8 is also elevated in major depression, while IL-10 and interferon gamma levels vary between early responders and those with treatment resistance." (PMID 40428308, 2025). "One study has shown that interferon gamma and interleukin 2 can trigger depression when used therapeutically." (PMID 37069633, 2023).